IL6 (interleukin 6)
Diseases named in the same sentence as IL6 in open-access papers (continued):
Sharing a sentence is not in itself a finding about the gene and the disease.
lepromatous leprosy (4 papers, 2016 to 2025). A chronic communicable infection which is a principal or polar form of leprosy. "Simultaneously, presence of Th17 related cytokines (TGF-β, IL-6, IL-17 and IL-23) decreased the number of FoxP3+ Treg cells concomitantly increasing IL-17 producing CD4+ cells in lepromatous leprosy." (PMID 26751584, 2016). "NLRP3 inflammasome’s immunohistochemical strong expression score is ahallmark of the Lepromatous Leprosy - The immunohistochemicalexpression of NLRP3, caspase-1, caspases-4/5, IL-1β, IL-6, and IL-18 between thegroups presented statistically significant differences in the scores." (PMID 32130367, 2020).
LGL leukemia (4 papers, 2017 to 2025). "LGL leukemia patients are also characterized by increased IL-6 levels, mainly caused by persistent STAT3 stimulation, and therefore, the inhibition of IL-6 signaling leads to a decrease in phosphorylated STAT3, thereby reducing LGL leukemic cell survival." (PMID 38610985, 2024). "Consistently, when we triggered STAT3 phosphorylation with IL-6 (20 ng/ml) or IL-15 (20 ng/ml), key cytokines in LGL leukemia development, after one hour culture we observed an increase of Fas ligand transcription levels (1.59- and 2.01-fold after IL-6 and IL-15, respectively)." (PMID 28977911, 2017). "In addition, circulating levels of IFN-α2, IFN-γ, monocyte chemoattractant protein-1, epidermal growth factor, IL-6, IL-8, IL-10, IL-1β, IL-12p35, IL-1Ra, and MIP1-a are increased in the sera of LGL leukemia patients." (PMID 33445786, 2021).
localized scleroderma (4 papers, 2021 to 2025). Localized scleroderma is the skin localized form of scleroderma characterized by fibrosis of the skin causing cutaneous plaques or strips. "The most severe form of localized scleroderma is pansclerotic morphea, which causes fibrosis of all layers of the skin, and the childhood form was recently found to have elevated IL-6 expression regulated by STAT4 gain of function mutations." (PMID 37669366, 2023). "Elevated IL-6 levels in morphea patients have prompted trials of tocilizumab, an anti-IL-6 monoclonal antibody, with intravenous administration leading to improvement in severe pediatric cases, especially in combination with methotrexate." (PMID 41010839, 2025). "Recently, there has been a growing interest in the use of tocilizumab, as considerably high serum levels of IL-6 have been found in patients with localized scleroderma." (PMID 40430462, 2025). "IL-6 is elevated in the skin and blood of patients with localized scleroderma and SSc and was recently identified to be overexpressed by fibroblasts of patients with childhood-onset pansclerotic morphea." (PMID 37669366, 2023). "IL-6 inhibition can be an effective target in localized scleroderma, as serum levels of soluble IL-6 receptor have been found to be increased in patients with localized scleroderma compared with healthy controls." (PMID 34640533, 2021).
lysosomal disorder (4 papers, 2016 to 2024). "Given the increased secretion of pro-inflammatory IL-6 observed in MCs treated with LpX in the presence of amiodarone, amiodarone and other drugs that cause phospholipidosis could potentially exacerbate the renal disease associated with FLD." (PMID 26919698, 2016). "Chronic stimulation of the immune system is a hallmark of many lysosomal disorders, including GD, and it is characterized by a markedly elevated level of proinflammatory cytokines, such as Interleukin-1β (IL-1β), Tumor Necrosis Factor- α (TNF-α), and/or Interleukin-6 (IL-6), and chemokines." (PMID 37446383, 2023).
macular degeneration (4 papers, 2022 to 2025). Loss of vision in the central portion of the retina (macula), secondary to retinal degeneration. "In response to stress, RPE cells secrete several cytokines, including interleukins 6 and 8 (IL-6, IL-8), and RPE-mediated inflammation is thought to be pathogenic in macular degeneration." (PMID 35806007, 2022). "Additionally, macular degeneration is associated with increasing levels of vascular endothelial growth factor (VEGF), monocyte chemotactic protein-1 (MCP-1), IL-6, and IL-8 in the aqueous humor." (PMID 38327497, 2024). "R9-SOCS3-KIR was particularly effective against the pathways acting through STAT3, e.g. IL-6 and VEGF-A mediated responses that lead to macular degeneration." (PMID 39104531, 2024).
malignant pleural mesothelioma (4 papers, 1998 to 2025). A malignant neoplasm that arises from mesothelial cells in the pleura and shows a diffuse growth pattern. "The relationship between interleukin 6 (IL-6) levels and clinical parameters was studied in 25 patients with malignant pleural mesothelioma." (PMID 9528833, 1998). "Although there has been only recent interest in IL-6 pathobiology in malignant peritoneal mesothelioma (MPM), IL-6 has long been suspected to contribute to pathophysiology of pleural malignant mesothelioma (MM)." (PMID 38689325, 2024).
manic episodes (4 papers, 2022 to 2024). "Compared to healthy people, BD patients with acute manic episodes had significantly increased serum IL-6, TNF-α, IL-1RA, and sIL-2R." (PMID 37662097, 2023). "As discussed in the introduction, there is some evidence that the frequency of depressive and manic episodes is related to serum IRS (sIL-1RA, IL-6) and CIRS (IL-10) biomarkers and to the stimulated expression of activation markers." (PMID 35406747, 2022). "Increased levels of IL-6 and TNF-α have also been noted during manic episodes." (PMID 38672750, 2024). "In patients experiencing a manic episode, pro‐inflammatory cytokines (e.g., TNF‐α, IL‐1, IL‐6), soluble receptors of IL‐2, soluble TNF‐α receptor type 1 (sIL‐2R and sTNFR1, respectively), and C reactive protein (CRP) are generally increased when compared to a control population." (PMID 34590391, 2022). "Also, the serum TNF-α was elevated in patients with depressive or manic episodes but not in euthymia, while IL-6 remained elevated regardless of the disease state." (PMID 37662097, 2023).
membranous nephropathy (4 papers, 2013 to 2023). "In patients with primary membranous nephropathy, increased expression of IL‐6 secreted by MDSCs expands MDSCs and increases Arg‐1 production for Th17 cell differentiation and IL‐17A production." (PMID 37382257, 2023). "Together, these results suggested that changes in IL-6 or IL-1β concentrations are closely related to the pathogenesis of membranous glomerulonephritis." (PMID 23990847, 2013). "This study is the first to report the effects of skimmin, a major constituent present in H. paniculata, on IL-1β and IL-6 protein expression in membranous glomerulonephritis." (PMID 23990847, 2013). "Immunohistochemistry results in the present study suggest that skimmin may inhibit B cell maturation and function by decreasing IL-6 levels in kidneys, leading to beneficial effect on membranous glomerulonephritis." (PMID 23990847, 2013).
Meniere disease (4 papers, 2022 to 2024). A disease of the inner ear (labyrinth) that is characterized by fluctuating sensorineural hearing loss; tinnitus; episodic vertigo; and aural fullness. "IL-6 also induces excessive production of vascular endothelial growth factor, resulting in enhanced angiogenesis and increased vascular permeability, which is associated with progressive hearing loss in Meniere’s disease." (PMID 38393014, 2024). "With regard to TNF-α pathway, IL-6 and NKFB have been found to have a significant prognostic role in a study on 43 patients with SSNHL compared with 10 patients with non-idiopathic SSNHL (Meniere’s disease, perilymph fistula, and bilateral progressive sensorineural hearing loss)." (PMID 35888682, 2022).
microcephaly (4 papers, 2015 to 2024). A congenital or acquired developmental disorder in which the circumference of the head is smaller than normal for the person's age and sex. "Increased levels of pro-inflammatory cytokines (e.g., IL-6 and TNF-α) have been associated with an augmented risk for microcephaly in preterm newborns." (PMID 38605125, 2024). "The risk of microcephaly was increased in newborns with hyperEPO+ISSI (ISSI defined by CRP, SAA, MPO, IL-6, TNF-α, TNF-R2, IL-8, MCP-1, ICAM-1, E-SEL, red), often more prominently than for ISSI alone." (PMID 25793991, 2015). "A polyfunctional immune activation associated with increased CCL2, CXCL10, IL-6, IL-8, VEGF, and G-CSF levels but decreased levels of IL-13 was also described in the amniotic fluid of ZIKV-positive pregnant women whose infants had microcephaly." (PMID 29768624, 2018).
mitral valve disease (4 papers, 2022 to 2025). "We created a decision tree prediction model including preoperative p-tau181, IL-6, and the severity of mitral valve disease (training data: AUC = 0.672, p < 0.0001; validation data: AUC = 0.642, p < 0.05)." (PMID 41429986, 2025). "Our results demonstrate that the combined assessment of preoperatively measured p-tau181 and IL-6, preoperative mitral valve disease, cognitive performance and female sex, significantly predicts POD." (PMID 41429986, 2025). "Moreover, we assessed IL6 and HCN expression in dilated left atrial samples from patients with mitral valve disease, an AF-prone condition." (PMID 39596280, 2024).
motor neuron disease (4 papers, 2014 to 2024). "The effect of IL-6 deficiency on the severity of motor neuron disease was examined using cohorts of SOD1 TG/IL-6(+/+) mice and SOD1 TG/IL-6(-/-) mice." (PMID 27070121, 2016). "On the other hand, recent data indicate that IL6-driven inflammation is evident in progressive MS and in motor neuron disorders, which are both characterised by a disabling course." (PMID 24818159, 2014). "Given that the involvement of IL-6 in the pathophysiology of ALS models remains unanswered, we have assessed whether IL-6 deficiency influences the onset and progression of motor neuron disease in a murine model of ALS." (PMID 27070121, 2016). "In conclusion, our data suggest that IL-6 is not a key factor in motor neuron disease caused by SOD1 mutation." (PMID 27070121, 2016). "Reducing HIPK2 activity improves phenotypes in mouse models of motor neuron disease ALS and IL6 levels, and the splicing of Fnip1 is altered in ALS conditions." (PMID 39337533, 2024). "However, at the end stage (155–175 days of age), hind limb extension was impaired in both SOD1 TG/IL-6(-/-) mice and SOD1 TG/IL-6(+/+) mice, suggesting the motor neuron disease progressed similarly in these mutant mice." (PMID 27070121, 2016).
MRSA pneumonia (4 papers, 2013 to 2025). "MRSA pneumonia was associated with high concentrations in BALF of proinflammatory cytokines (TNF-α, IL-6) and chemokines (CXCL2, CXCL5)." (PMID 35972289, 2022). "Indeed, LZD inhibits the secretion of IL-6, TNF-α, and IL-1RA in LPS-stimulated PBMCs and reduces bronchoalveolar lavage (BAL) fluid levels of cytokines including IL-6, IL-1β, Interferon-γ, and IL-17 in a mouse model of MRSA pneumonia." (PMID 33042867, 2020). "MRSA pneumonia induced an increase in IL-6, G-CSF, TNFα, IL-1β, and IL-10." (PMID 24204769, 2013).
mucormycosis (4 papers, 2015 to 2022). "We hypothesize that the excessive dose of corticosteroids, especially in combination with IL-6 inhibitors like tocilizumab might have contributed to the development of mucormycosis." (PMID 36458102, 2022). "While IFN-γ/STAT1 signaling was similar between groups, naïve T cells from patients with IA, but not those with mucormycosis, exhibited reduced responsiveness to IL-6 as measured by STAT3 phosphorylation." (PMID 25835547, 2015).
Myocardial necrosis (4 papers, 2019 to 2025). Irreversible damage to heart tissue (myocardium) due to lack of oxygen after a heart attack (myocardial infarction). "IL-1β and IL-6 have been demonstrated as proinflammatory cytokines and were associated with myocardial necrosis." (PMID 35928492, 2022). "In STEMI patients, circulating levels of IL-6 have been shown to correlate with high levels of cTnI thereafter, with myocardial necrosis size." (PMID 38017432, 2023). "Several studies indicate that the highest IL-6 levels are reached on the first day after MI (as a result of myocardial necrosis), and thereafter, a rapid decline occurs, obtaining a stable level after a few weeks (depending on the source from 2 weeks to 6 months)." (PMID 31739518, 2019). "IL-8 and IL-6 were less strongly related to acute cardiac injury (not shown) and IL-18 levels were similar in those with versus those without myocardial necrosis." (PMID 39969260, 2025).
Nephroblastoma (4 papers, 2020 to 2023). An embryonal neoplasm characterized by the presence of epithelial, mesenchymal, and blastema components. "Improper regulation of IL-6 is implicated in the progression of Wilms tumor, suggesting that antagonizing calmodulin could indirectly help slow tumor progression by reducing IL-6 expression." (PMID 31797619, 2020). "And the expression of inflammatory factors IL6 and IL8 was down-regulated, which inhibited the occurrence and development of nephroblastoma." (PMID 37058032, 2023). "Transgenic-adipo-PGC-1α mice displayed reduced adipocyte hypertrophy, associated with a reduction in molecules within the TGF-β signaling pathway, and of the inflammatory markers nephroblastoma-overexpressed/cellular communication network factor 3 (NOV/CCN3), Twist1, and IL-6." (PMID 35740043, 2022). "Therefore, the upregulation of heme and ROS due to a decreased HO activity increases pre-adipocyte differentiation, as well as adipogenesis and the release of inflammatory adipokines such as nephroblastoma overexpressed gene (NOV), tumor necrosis factor-α (TNFα), and Interleukin-6 (IL-6)." (PMID 32751794, 2020).
nephropathia epidemica (4 papers, 2010 to 2021). "Categorical variables associated with the severity of the disease in nephropathia epidemica patients, divided into four groups according to maximum plasma interleukin-6 and C-reactive protein levels." (PMID 20500875, 2010). "IL-6-induced STAT3 activation was observed in mice with HgCl2-induced AKI, and IFN-γ has been shown to activate STAT1 in glomerular mesangial cells in an aristolochic acid nephropathy mouse model." (PMID 33511217, 2021).
neuroendocrine tumors (4 papers, 2015 to 2024). "In neuroendocrine tumor cells, the signal transducer and activator of the transcription 3 (STAT3)/IL-6 axis has been implicated in proliferation, survival, and differentiation through MAPK-dependent signaling." (PMID 36294509, 2022).
neurotoxicity (4 papers, 2019 to 2026). Toxicity that causes injury to the central or peripheral nervous system or damages its function. "Neurotoxicity is a pathological phenomenon seen in neuroHIV that was also observed through transfer of cell-free CM from Ephb2 activated microglia onto neurons, which our data suggest is a consequence of the assortment of pro-inflammatory secreted factors (IL-6, CXCL10, TNFα, IL-1β etc.)." (PMID 40588746, 2025). "Neurotoxicity appears to present later than CRS, may take longer to resolve, and is less responsive to IL-6-targeted therapies than CRS." (PMID 31226876, 2019).
normal-tension glaucoma (4 papers, 2021 to 2025). "For instance, the lncRNA metastasis associated lung adenocarcinoma transcript 1 (MALAT1) has been shown to act as a ceRNA and regulates the IL-6 expression by sponging miR-1, thus affecting the severity of normal-tension glaucoma." (PMID 35800083, 2022). "In normal-tension glaucoma (NTG), the serum IL-6 level is related to the disease severity." (PMID 40486511, 2025).
oropharyngeal carcinoma (4 papers, 2019 to 2026). Carcinoma, predominantly squamous cell, arising from the epithelial cells of the oropharynx. "Allen and his team examined serum samples from patients with oropharyngeal carcinoma for the presence of various factors, including IL-6, during and after chemoradiation." (PMID 33922946, 2021).
oropharyngeal squamous cell carcinoma (4 papers, 2016 to 2025). "It focused on the longitudinal changes in serum levels of specific factors like IL-6, IL-8, VEGF, HGF, and GRO-α in 30 patients undergoing chemoradiation therapy for stage III/IV oropharyngeal squamous cell carcinomas." (PMID 38672104, 2024). "To evaluate the expression pattern and clinical importance of myoferlin, IL-6 and nanog in HNSCC, we assessed the expression of these biomarkers in TMA's constructed using 211 surgically treated oropharyngeal squamous cell carcinoma samples." (PMID 26919244, 2016).
overlap syndrome (4 papers, 2017 to 2025). "Nevertheless, in a subgroup of patients with overlap syndrome, but not in other patients, levels of IL-6 correlated with immunologic parameters, such as ESR and the serum level of γ-globulins." (PMID 28299346, 2017). "The group of patients with overlap syndrome had worse right heart function parameters than the group with OSAHS alone, and this may be related to higher inflammatory factors (hypersensitive C‐reactive protein, PCT, IL‐6)." (PMID 39978401, 2025). "Despite the difference in clinical parameters, the difference in IL-6 levels with the controls was somehow more marked in patients with AIH and the whole group of AILD, but not in patients with overlap syndrome." (PMID 28299346, 2017).
panic disorder (4 papers, 2018 to 2022). An anxiety disorder characterized by multiple unexpected panic attacks with persistent concern of recurring attacks. "C-reactive protein levels, which are increased following interleukin 6 secretion, were observed to be elevated in a large cohort of individuals diagnosed with panic disorder, agoraphobia, and generalized anxiety disorder." (PMID 32906843, 2020). "Various studies have reported pro-inflammatory cytokines, including interleukin 1β, interleukin 6, and tumor necrosis factor alpha, are enhanced in panic disorder patients." (PMID 32906843, 2020). "Higher levels of IL-1β and IL-6 in panic disorder patients may interfere with differentiation and activation of naïve CD8+ T, possibly reducing inflammation." (PMID 33208194, 2020). "Those with panic disorder have also demonstrated increased IL-1β and IL-6." (PMID 33208194, 2020).
papilloma (4 papers, 2013 to 2023). A benign epithelial neoplasm that projects above the surrounding epithelial surface and consists of villous or arborescent outgrowths of fibrovascular stroma. "We observed that the Vav2/Vav3-dependent Tgfa, Hgf, Fgf7, and Il6 transcripts showed reduced abundance in papillomas derived from Vav2/Vav3-deficient mice when compared to the levels present in control mouse tumors." (PMID 23935450, 2013). "The papillomas in Mcpip1eKO mice were characterized by increased protein levels of IL-6, IL-33 and TGF-β1." (PMID 34903245, 2021). "Flow cytometry analysis of papillomas showed generally low immune cell infiltration in both genotypes; however, CD11b+ myeloid cells and pro-tumor PMN-MDSCs trended higher in the knockout mice, which was corroborated by higher IL-6 (produced by myeloid cells) mRNA expression in CB2-/- papillomas." (PMID 37175480, 2023).
periapical abscess (4 papers, 2021 to 2023). "However, periapical abscesses showed a significant low expression level of SARS-CoV-2 receptors and higher expression of IL-6." (PMID 34749700, 2021).